INS (insulin)
Diseases named in the same sentence as INS in open-access papers (continued):
Sharing a sentence is not in itself a finding about the gene and the disease.
dementia (continued). "Patients with T2DM using insulin had higher risk of all-cause dementia than those without insulin (RHR 1.54; 95%CI 1.00–2.37)." (PMID 36804018, 2023). "Specific analysis with dementia subtypes showed that compared to people without using insulin, insulin use nearly doubled the risk of VD (RHR 1.92; 95%CI 1.06–3.48)." (PMID 36804018, 2023). "They found that the HRs of dementia among users of metformin + pioglitazone were 0.56, 0.66, 0.69, and 0.98, respectively, when compared with metformin‐based use of sulfonylureas, acarbose, meglitinide, and insulin." (PMID 36660897, 2023). "However, it should be mentioned that because this is the last step, dementia would be more likely in those receiving insulin as T2DM has progressed further along." (PMID 38152822, 2023). "Chronic insulin signalling, hyperinsulinaemia, is mechanistically associated with increased incidence of chronic diseases of ageing, including the following: CVD, cancer, cognitive decline and dementias such as Alzheimer’s and Parkinson’s diseases, and T2DM." (PMID 37760052, 2023). "Adherence to metformin shows a reduction in the risk of developing dementia, irrespective of the patient's gender, age, or concurrent insulin treatment." (PMID 38152822, 2023). "Three studies found that adherence to metformin demonstrated an association with reduced risk of developing dementia regardless of insulin use and that the incidence rates of AD were significantly lower." (PMID 38152822, 2023). "Epidemiological and clinical studies have overwhelmingly confirmed that defective insulin signaling in the brain plays a central role in the early stages of dementia, a primary feature of sporadic Alzheimer’s disease (AD) and AD- Related Dementias (ADRD) pathology." (PMID 36609440, 2023). "Researchers have also found that patients with dementia have significant insulin resistance in their hippocampi, suggesting that dysregulation of brain insulin signaling pathways may play an important role in cognitive dysfunction." (PMID 37214403, 2023). "Patients with T2DM using insulin had higher risk of all-cause dementia than those without insulin, with an RHR (95%CI) of 1.54 (1.00–2.37)." (PMID 36804018, 2023). "Moreover, some observational studies have found peripheral insulin administration to be ineffective; in some cases, it led to worsening dementia." (PMID 35742986, 2022). "Other blood biomarkers that could be elevated in the preclinical stage of dementia, such as insulin, fibroblast growth factor 21, lipocalin-2, or trimethylamine N-oxide may need to be considered to help increase the discriminative properties." (PMID 36292406, 2022). "Given the growing interest in dementia therapeutics targeting impaired insulin metabolism and IGF signaling, IGFBP5 may be a useful circulating biomarker to predict dementia risk for future clinical trials." (PMID 35513854, 2022). "At the early stages of dementia devoid of Aβ accumulation in the brain, nose-to-brain delivery of L-penetratin/insulin appeared to have the therapeutic effect by preventing the mild cognitive dysfunction of early dementia, whereas it did not prevent severe recognitive dysfunction." (PMID 36452220, 2022). "Multiple studies have confirmed that improving brain insulin signaling is essential for dementia." (PMID 35892598, 2022). "Both insulin and sulfonylurea did not lower the risk of dementia, instead increasing the risk in some cases." (PMID 35742986, 2022). "Logistic regression analysis using only DM subjects showed that a history of metformin use reduced the risk of delirium in patients with DM (OR = 0.50, 95% CI: 0.32–0.79, p = 0.003) even after controlling for age, sex, dementia status, BMI, and history of insulin use." (PMID 36399107, 2022). "Consequently, dysregulated insulin/IGF signaling and insulin resistance in the CNS have been linked to an increased risk of dementia, including AD, which is sometimes referred to as type 3 diabetes." (PMID 34795562, 2021).
dementia (continued). "Pharmacological studies have suggested that i.n. insulin and oxytocin could improve early cognitive recognition in dementia and autism disorder." (PMID 34683967, 2021). "Individuals who received insulin injections or oral hypoglycemic medications had a higher risk of dementia incidence than those who did not (OR: 2.635, 95% CI: 1.294–5.365)." (PMID 33213100, 2020). "A similar approach for dementia would be valuable, but it requires consideration of a larger set of predictors (e.g., smoking, cardiovascular disease, glucose, insulin, and inflammatory markers) with careful categorization to best reflect the continuum of risk." (PMID 32423410, 2020). "In addition, the insulin resistance pathway, such as serine/threonine-protein kinase (AKT) phosphorylation, also plays an important role in dementia risk." (PMID 33352859, 2020). "Administration of exogenous insulin (through controlled infusion while maintaining constant glucose levels or through intranasal administration) has been suggested as a promising therapeutic approach against dementia and AD." (PMID 30768625, 2019). "Given the high prevalence of dementia in advanced stages of PD, the impairment of multiple molecular cascades, such as insulin signaling, may amplify the neuropathological processes that lead to dementia before the overt manifestation of dementia." (PMID 29515352, 2018). "In the next years, the results of the ongoing larger clinical trials will provide further information about how metabolic status of AD patients interfere on treatment success and also the potential of anti-diabetic therapies in dementia, specially, insulin intranasal use as a possible AD therapy." (PMID 30542257, 2018). "Therefore, our previous work concluded that efficient delivery of insulin to the brain is an effective therapy in the early stage of dementia, whereas it is unfavorable in the severe stage with Aβ accumulation." (PMID 30518944, 2018). "Using insulin did not affect the risk of dementia, but oral hypoglycaemic agents appeared to reduce the risk of developing dementia (HR 0.93, 95% CI 0.90–0.96)." (PMID 30182156, 2018). "The nonlinear association between fasting insulin and risk of dementia is further illustrated with the use of proportional hazard regression with restricted cubic splines." (PMID 29997193, 2018). "The use of oral hypoglycaemic agents (and statins), but not insulin, has been linked to a lower risk of developing dementia." (PMID 30182156, 2018). "Meanwhile, some studies further demonstrated that the therapeutic effect of insulin on early-stage dementia could be accomplished by its intranasal administration." (PMID 30518944, 2018). "The results of this study provide strong clinical evidence supporting the notion that nonpsychotic dementia is associated with increased levels of circulating insulin and decreased levels of insulin in the CSF." (PMID 29445549, 2017). "Some authors have argued that abnormal insulin metabolism is caused by aging and does not share a causal relationship with nonpsychotic dementia." (PMID 29445549, 2017). "A random-effects meta-analysis was performed, and the results showed that high insulin levels were associated with a higher risk of nonpsychotic dementia than was observed in the HCs (Hedges' g = 0.334, 95% CI = 0.249 to 0.419, and P = 0.000)." (PMID 29445549, 2017). "Furthermore, administration of insulin has been shown to improve memory in AD patients suggesting a potential therapeutic avenue for dementia treatment." (PMID 26095650, 2016). "The pathological prion protein, PrPSc, deposits in the form of extracellular aggregates and leads to dementia, raising the question as to whether prion pathogenesis may also be affected by insulin resistance." (PMID 26658276, 2015). "Disruption of insulin signaling is known to make neurons vulnerable to metabolic stress and accelerate neuronal dysfunction leading to decreased cognitive ability and development of the symptoms of dementia." (PMID 26161865, 2015).
dementia (continued). "Considering that its major action is on the liver, it has been reported in recent years that it can also cross the BBB, which given its insulin-sensitizing properties suggests that it may play a role in insulin resistance and dementia." (PMID 25346723, 2014). "Interestingly, a recent study used intranasal delivery of insulin to the brain as a therapy for human dementia patients with some improvement seen in memory and self care tasks." (PMID 23585733, 2013). "Since IGF and GSK-3β are also perturbed in the brain of Guam and Japanese ALS/PDC patients, and insulin resistance is an established risk factor for dementia, the cycad genotoxins might induce tau pathology in GD and PDC by inducing brain insulin resistance." (PMID 22073019, 2011). "Notably, our study’s sensitivity analysis stratified by glycemic control and insulin use did not significantly change the association between age at diagnosis and dementia, suggesting that other pathophysiologic mechanisms are involved." (PMID 39535979, 2024). "Moreover, intranasal insulin has been shown to have a favorable safety profile compared to intravenous insulin, making it an attractive candidate for further study in the treatment of dementia." (PMID 37511207, 2023). "A systematic review and meta-analysis including 144 studies found that T2DM patients who used insulin had 1.36 times higher risk of all-cause dementia than those without insulin therapy, while this review did not separate the analysis by sex and dementia subtypes." (PMID 36804018, 2023). "Therefore, intranasal insulin administration may have a therapeutic effect in the treatment of dementia." (PMID 35742986, 2022). "Notably, defects in insulin signaling in the brain may contribute to neurodegenerative disorders and damage of the cognitive system leading to dementia states." (PMID 35406040, 2022). "Moreover, a Bayesian network meta-analysis included 17 studies containing 1,258,879 individuals, and 3 of the studies with insulin use found that insulin did not reduce the risk of dementia." (PMID 35742986, 2022). "Consequently, loss of insulin/IGF-1 signaling in the brain, mediated by both the IR and the IGF1R, has generally been associated with an elevated risk of AD, cognitive decline, (premature) dementia, depression, and anxiety." (PMID 32226608, 2020). "Insulin use was associated with risk of dementia but not AD." (PMID 30768625, 2019). "Insulin administration has been shown to be the only significant, independent negative predictor of low HbA1c values after controlling for factors such as age, BMI, leukocyte number, low glomerular filtration rate, dementia, orthostatic hypotension, or taking sulfonylurea." (PMID 31477024, 2019). "However, sensitivity analyses showed that none of the covariates that correlated with serum insulin explained the reported associations with dementia endpoints, underlining the fundamental importance of insulin for the etiology of dementia." (PMID 29997193, 2018). "The present meta-analysis was aimed at determining whether nonpsychotic dementia is associated with altered levels of insulin in the blood or cerebrospinal fluid (CSF)." (PMID 29445549, 2017). "In addition, the insulin/IGF1 signaling pathways have been implicated in dysregulated synaptic maturation and may play key roles in brain aging and dementia as well as learning and cognitive functions in rodent models." (PMID 27370225, 2016). "GSK-3β is an essential kinase in the insulin pathway that serves as a vital link between the pathologies of T2DM and dementia." (PMID 38660514, 2024). "Another possible explanation is that an indication for insulin is a surrogate indicator of long-lasting and more severe T2DM, which already increases the possibility of dementia." (PMID 39434474, 2024).
dementia (continued). "Furthermore, insulin minimizes Aβ toxicity by acting as a neuroprotector, where insulin inhibits the fibril formation of Aβ in a cell-free environment and on the surface of human brain pericytes, which highlights how insulin may serve to prevent the onset and progression of dementia." (PMID 37372995, 2023). "The results of these experiments showed that N2B delivery of exendin-4, co-administrated with L-penetratin and supplemented with a low dose of insulin, improved cognitive and spatial functions in the SAMP8 mouse model of dementia." (PMID 37371113, 2023). "The proteins were related to one or more biological systems that are relevant to dementia etiology: activation of the immune system, blood‐brain barrier (BBB) breakdown, vascular pathology, and central insulin resistance." (PMID 34338426, 2022). "However, the assertion that brain insulin resistance is a salient feature of aging, T2D and dementias require a careful evaluation of whether brain insulin resistance is identical at the molecular and physiological level to insulin resistance as traditionally defined in peripheral tissues." (PMID 35798912, 2022). "Ten of the non‐insulin trials include individuals with MMSE scores of 20 or above consistent with early AD; the other trials include patients with mild‐moderate AD dementia." (PMID 35128745, 2022). "A previous study found that brain insulin resistance, including impaired insulin receptor signaling and insulin‐like growth factor‐1 (IGF‐1) signaling, leads to cognitive dysfunction in dementia by aggravating neuronal cell death and synaptic dysfunction." (PMID 33945675, 2021). "The onset and progression of dementia are influenced by a variety of LCN2‐mediated mechanisms including inflammation, insulin resistance, iron accumulation, immune response, neuronal cell damage, and glia dysfunction." (PMID 33945675, 2021). "Differences between users and non-users of insulin, metformin and sulfonylurea were assessed in each cohort for cognitive and brain MRI measures using linear regression models, and cognitive decline and dementia/AD risk using mixed effect models and Cox regression analyses, respectively." (PMID 30768625, 2019). "Overall, our results indicated that the significant heterogeneity observed in the patients with increased insulin and nonpsychotic dementia could have been caused by a variety of factors, such as gender, sampling differences, and the severity of nonpsychotic dementia." (PMID 29445549, 2017). "Therefore, both negative and positive correlations have been observed, resulting in controversy regarding whether high insulin levels or low insulin levels cause nonpsychotic dementia." (PMID 29445549, 2017). "The tau pathology in the STZ rodent model of dementia is preceded by early changes in the phosphatidylinositol-3-kinase (i.e., PI3K, phospho-Akt, GSK-3β) insulin/IGF-signaling pathway." (PMID 22073019, 2011). "Within the PFC, Akt S473 phosphorylation (a marker of insulin‐specific Akt activation) was significantly higher in AD individuals with no impact of sex (main effect of dementia, F = 8.580, p = 0.0064)." (PMID 41031399, 2025). "Insulin did not appear to influence the development of dementia, MCI, or cognitive decline in the two-case-control and two cohort studies we meta-analyzed, with the follow-up duration of 5 to 17 years." (PMID 40017057, 2025). "As shown in our descriptive analysis, insulin was more likely to be prescribed to patients with dementia than those without dementia, likely due to higher rates of comorbidities in people with dementia." (PMID 38673407, 2024). "In this regard, considering the well-known insulin sensitizer role of metformin, which includes the improvement of GLUT4 expression/translocation in adipose and muscle tissues, we should direct attention to this promising drug to fight dementia." (PMID 38003671, 2023).
dementia (continued). "Remarkably, L-penetratin resulted in being effective in enhancing the therapeutic efficacy of insulin, improving mild cognitive dysfunction during the early stage of dementia in the absence of Aβ accumulation." (PMID 37371113, 2023). "How the use of insulin therapy moderates the link between T2DM and dementia and whether there is a sex difference remains unclear." (PMID 36804018, 2023). "Nasal insulin enhances cognitive performance in people with dementia, but this has not been observed in older adults with DM." (PMID 36258952, 2022). "For incidence of non-AD dementia, insulin (4.76% vs. 5.45%, RR: 0.87; CI: 0.86–0.89, p-value < 0.001) use was associated with a significantly lower risk reduction than all other drug categories." (PMID 35601622, 2022). "A trial of memory effects 15 minutes after intranasal insulin in normal controls or patients with mild‐moderate AD dementia or MCI (N = 61) showed improvement in those without the APOE‐4 genotype." (PMID 35128745, 2022). "In addition, our results suggest that insulin or sulfonylureas should be used with caution in older patients with T2DM and dementia, while the metformin seems to be safer." (PMID 35055382, 2022). "No dementia or neurological complications have been observed with other drugs, such as thiazolidinediones, sulfonylureas, or insulin." (PMID 36497027, 2022). "The use of antioxidant supplementation, memantine, vitamin E, and intranasal insulin did not have relevant effects for the treatment of dementia in people with DS." (PMID 35630721, 2022). "Increasing peripheral insulin concentrations does not exhibit a beneficial effect on dementia; thus, it is important to increase insulin levels in the central nerve system." (PMID 35742986, 2022). "A current nested case control research evaluating the implications of a range of antidiabetic drugs in dementia has shown that sulphonylureas/glinides, insulin, and thiazolidinediones (TZDs) had no positive impact on development of dementia." (PMID 34069618, 2021). "Decreased insulin levels and reduced binding of insulin to insulin receptors were reported in the cortex of elderly individuals without dementia." (PMID 32733190, 2020). "It is clear that the role of insulin/IGF-1 signaling in aging (beyond examining lifespan in worms, flies, and mice) should also be considered in light of the impact of this signaling pathway on dementia (cognition) and neurogenesis." (PMID 32226608, 2020). "DMD patients were more often male and exhibited more acarbose use but less insulin use than DM patients without dementia (p<0.05)." (PMID 32805719, 2020). "PS-matched analyses showed increased annual insulin dispensation (β difference 0.97%) and lower increase in DPP-4i (–0.58%), GLP-1a (–0.13%), and SGLT-2i (–0.21%) dispensation in dementia patients compared to dementia-free controls." (PMID 32741836, 2020). "A study of 110 PD patients (53 with PD and dementia (PD/D) and 57 PD without dementia evaluated glucose and insulin levels after a 2 hours oral glucose tolerance-test." (PMID 31231176, 2019). "Our results confirmed a nonlinear association in a female population, with high risk at low insulin values that was not attributable to preclinical dementia or impaired insulin secretion." (PMID 29997193, 2018). "In both cases, lack of insulin or excess of insulin due to insulin resistance lead to the convergent development of dementia." (PMID 29743868, 2018). "In the present study we have undertaken a more detailed analysis of the insulin and IGF-1 signaling pathway to dissociate the synergistic or additive connection between the early pathological events of dementia, such as high levels of Aβ and neuroinflammation, and the small focal ischemia." (PMID 29572520, 2018). "The results suggest that insulin levels are higher in the peripheral blood in VD, AD, L, and MH patients while CSF insulin levels are lower in nonpsychotic dementia patients." (PMID 29445549, 2017).